IPCEF1 (interaction protein for cytohesin exchange factors 1)
Description:
Enhances the promotion of guanine-nucleotide exchange by PSCD2 on ARF6 in a concentration-dependent manner.
Synonyms: KIAA0403; PIP3-E; PIP3E
Tractability: Antibody: UniProt places it where antibodies can reach, with medium confidence; its Gene Ontology location is reachable by antibodies, with medium confidence; the Human Protein Atlas places it where antibodies can reach. PROTAC: its protein half-life has been measured.
Safety:
Unwanted effects reported when the protein is acted on. In parentheses: how it was acted on, where the effect was seen, and who reports it.
cocaine cue-reactivity (source: ClinPGx)
Gene: Protein-coding gene on chromosome 6 (154,154,496 to 154,356,803, reverse strand). Ensembl gene ENSG00000074706.
Subcellular location: Cytoplasm; Cell membrane
Subcellular location (Human Protein Atlas): Nuclear speckles; Plasma membrane; Cytoplasmic bodies; Nucleoli
Gene Ontology:
Molecular function: protein binding; oxygen carrier activity; peroxidase activity; protein-macromolecule adaptor activity
Biological process: enzyme-linked receptor protein signaling pathway; oxygen transport; response to oxidative stress; cellular oxidant detoxification
Cellular component: cytoplasm; plasma membrane
Genetic constraint (gnomAD): Loss-of-function variants: 15 observed, 33.33 expected, observed/expected ratio (o/e) 0.45, 90% interval 0.3 to 0.69. The upper end of that interval is the gene's LOEUF score, 0.69, which puts it in group 2 of 6, group 1 being the genes least tolerant of losing a copy. Missense variants: 345 observed, 436.1 expected, observed/expected ratio (o/e) 0.79, 90% interval 0.72 to 0.87. Synonymous variants: 145 observed, 169.83 expected, observed/expected ratio (o/e) 0.85, 90% interval 0.75 to 0.98.
Homologues: Orthologues: chimpanzee IPCEF1 (99% identical), macaque IPCEF1 (97% identical), rabbit IPCEF1 (82% identical), rat Ipcef1 (76% identical), guinea pig IPCEF1 (75% identical), mouse Ipcef1 (75% identical), pig IPCEF1 (68% identical), Drosophila melanogaster cnk (20% identical), Caenorhabditis elegans cnk-1 (10% identical). Paralogues in human: CNKSR2 (37% identical), CNKSR1 (24% identical), CNKSR3 (15% identical), SAMD3 (14% identical).
Diseases named in the same sentence as IPCEF1 in open-access papers:
IPCEF1 is named in the same sentence as 13 diseases in open-access papers, as found by Europe PMC text mining. Sharing a sentence is not in itself a finding about the gene and the disease. The quoted sentences say what the papers report.
thyroid cancer (3 papers, 2022 to 2024). "Echoing this, Ren, S's utilization of bioinformatics and Internet of Things technologies in cancer patient disease analysis revealed a correlation between higher IPCEF1 expressions with extended survival in thyroid cancer patients." (PMID 39513122, 2024). "Espinal-Enríquez and coworkers discovered that IPCEF1 was underexpressed in thyroid cancer." (PMID 35634509, 2022).
Papillary Thyroid Carcinoma (2 papers, 2020 to 2024). "Notably, the involvement of IPCEF1 in thyroid papillary carcinoma remains an uncharted territory deserving of comprehensive investigation." (PMID 39513122, 2024).
anaemia (1 paper, 2024). "Collectively, this evidence suggested that GNRS_28218, associated with IPCEF1, is likely to have a functional role in anaemia." (PMID 38364871, 2024). "CLL is frequently complicated by cytopaenias, either due to bone marrow infiltration or autoimmunity, and results in autoimmune haemolytic anaemia (AIHA), suggesting the potential involvement of IPCEF1 in anaemia." (PMID 38364871, 2024).
breast carcinoma (1 paper, 2016). "We identified two genes with a significant gain in correlation with PTEN in breast cancer samples with PTEN mutations (n = 27) compared to samples without PTEN mutations (n = 816), FASLG and IPCEF1." (PMID 27846853, 2016).
chronic lymphocytic leukaemia (1 paper, 2024). "A previous GWAS of chronic lymphocytic leukaemia (CLL) identified a susceptibility locus mapping to IPCEF1 (rs2236256, P = 2 × 10−10)." (PMID 38364871, 2024).
lymph node metastases (1 paper, 2024). "Notably, in the low IPCEF1 expression group, a significantly greater percentage of patients had advanced T stage (III-IV), lymph node metastases (N1), and higher TNM stages (III-IV) compared to early T stage (I-II), no lymph node metastases (N0), and lower TNM stages (I-II), respectively." (PMID 39513122, 2024).
sarcoma (1 paper, 2022). A usually aggressive malignant neoplasm of the soft tissue or bone. "Notably, amplification was the most common type of mutation, and S100A9, IPCEF1, and GPX7 were frequently amplified in sarcoma." (PMID 35143416, 2022).
cancer (2 papers, 2019 to 2024). A tumor composed of atypical neoplastic, often pleomorphic cells that invade other tissues. "Recent studies have suggested a possible link between IPCEF1 and cancer progression, although the exact mechanisms and implications remain largely unexplored 6-8." (PMID 39513122, 2024). "IPCEF1 (interaction protein for cytohesin exchange factors 1) has emerged as a critical player in cell signaling related to proliferation and migration in cancer progression." (PMID 39513122, 2024). "Our findings suggested that IPCEF1 is a cancer suppressor gene in the progression of PTC, influencing patient survival and prognosis through modulation of immune infiltration and signaling pathways." (PMID 39513122, 2024).
tumor (2 papers, 2022 to 2024). "To delve deeper into the role of IPCEF1 in PTC, we assessed the infiltration of immune cells in the tumor microenvironment and analyzed the correlation between IPCEF1 levels and different immune cell populations." (PMID 39513122, 2024). "Conversely, IPCEF1 expression was positively correlated with M1 macrophage infiltration, typically more abundant in normal tissues than in tumor tissues." (PMID 39513122, 2024). "Our results showed that IPCEF1 was negatively correlated with Tregs, which infiltrated more in tumor tissues than that in normal tissues." (PMID 39513122, 2024). "A lower expression of IPCEF1 may contribute to a more favorable prognosis by reducing Treg-mediated suppression of anti-tumor immunity." (PMID 39513122, 2024). "Our data suggest that IPCEF1 may facilitate the polarization towards M1 macrophages, thereby potentially hampering tumor progression in PTC." (PMID 39513122, 2024). "Additionally, studies have shown that IPCEF1 induces tumor metastasis by activating the Arf6 pathway." (PMID 35634509, 2022). "The results showed that the expression of IPCEF1, TFF3, GLT8D2, TPO and DIO1 were downregulated in the tumor group and DPP4, LRP4, CDH3, KCNJ2, CLDN1, GABRB2, FN1 were upregulated in the tumor group." (PMID 39513122, 2024). "Our findings indicated a negative correlation between IPCEF1 expression and M2 macrophage infiltration, which was higher in tumor tissues compared to normal tissues." (PMID 39513122, 2024).
IPCEF1 also shares sentences with these, for which no sentence is quoted: Autoimmunity (1 paper); colon cancer (1); hepatocellular carcinoma (1); thyroid tumor (1).